WDR1 (WD repeat domain 1)
Diseases named in the same sentence as WDR1 in open-access papers (continued):
Sharing a sentence is not in itself a finding about the gene and the disease.
Hypercholesterolemia (1 paper, 2022). An increased concentration of cholesterol in the blood. "Interaction analysis showed that ACTB formed the hub of the revealed network, being involved in many interactions with other accessory proteins (e.g., with upregulated CAP1, WDR1, GSN, RHOA, and ARPC1A), suggesting myocardial cytoskeleton rearrangement in response to hypercholesterolemia." (PMID 35806390, 2022).
liver fibrosis (1 paper, 2024). "Under the regulation of AAV interference of WDR1, a significant reduction in metastatic foci in the liver and a corresponding reduction in liver fibrosis in a mouse PDAC liver metastasis model has been detected." (PMID 38291031, 2024). "WDR1 is involved in the formation of liver fibrosis and provided favorable evidence for the view that tRF-GluCTC-0005 in PDAC derived exosomes promotes liver PMN formation through WDR1." (PMID 38291031, 2024). "This study also highlights the role of tRF-GluCTC in regulating WDR1 and its implications in HSC activation and liver fibrosis, and the molecular interactions in HSCs are expected to provide clues for subsequent target therapy." (PMID 38291031, 2024).
lung carcinoma (1 paper, 2021). "WDR1 was found to be upregulated and associated with poor prognosis in breast and lung cancer." (PMID 34044822, 2021).
Lupus (1 paper, 2025). "Further links of C3-LHF1 to Lupus and particularly lupus nephritis also come with its physical association in plasma to peroxidasin, a protein suggested to be an autoepitope in lupus nephritis, or lupus-linked proteins such as RPL22, and WDR1." (PMID 41145914, 2025). "While our data found a classical engagement of C3 with C3 and C4, nidogen-1 (NID1), and plasminogen (PLG), C3-LHF1 also engaged with other lupus- and autoimmune-related proteins, such as WDR1, RPL22, and PXDN, supporting its mechanism of interacting with surface binders." (PMID 41145914, 2025).
lymphoma (1 paper, 2021). A malignant (clonal) proliferation of B- lymphocytes or T- lymphocytes which involves the lymph nodes, bone marrow and/or extranodal sites. "As WDR1 has been shown to inhibit SDF-1-dependent migration of lymphoma cells, cell migration was studied by transwell assay in SU-DHL-1 cells upon overexpression of miR-1250-5p." (PMID 34044822, 2021). "MAPK1 and WDR1 are novel miR-1250-5p direct targets rendering inhibition of MAPK/ERK signaling and SDF-1-dependent cell migration, hence implicated in survival and dissemination of lymphoma." (PMID 34044822, 2021). "Moreover, MAPK1 and WDR1 are novel targets of miR-1250-5p, regulating MAPK/ERK signaling and SDF-1-dependent cell migration, hence implicated in cell survival and lymphoma dissemination." (PMID 34044822, 2021). "By contrast, in the absence of SDF-1, the inhibitory effect of cell migration by knockdown of WDR1 was weakened, confirming the oncogenic property of WDR1 in the promotion of SDF-1-dependent migration of lymphoma cell." (PMID 34044822, 2021).
meningitis (1 paper, 2023). A disorder characterized by acute inflammation of the meninges of the brain and/or spinal cord. "In this study, we identified two RAVE complex components, Rav1 and Wdr1, in the fungal meningitis pathogen Cryptococcus neoformans, and analyzed their roles." (PMID 37812645, 2023).
osteoporosis (1 paper, 2023). A condition of reduced bone mass, with decreased cortical thickness and a decrease in the number and size of the trabeculae of cancellous bone (but normal chemical composition), resulting in increased fracture incidence. "In addition, target interaction network analysis by network-based visual analysis (miRNet) showed that five genes (GAPDH, PLOD1, LMNA, WDR1, and P4HB) with five miRNAs (hsa-let-7a/b-5p, hsa-let-7b-5p, hsa-mir-16-5p, hsa-mir-18a-5p, and hsa-mir-192-5p) were associated with osteoporosis by DisGeNET." (PMID 38132172, 2023).
osteosarcoma (1 paper, 2021). A usually aggressive malignant bone-forming mesenchymal neoplasm, predominantly affecting adolescents and young adults. "The selected 5 MAGs (MAP3K5, PML, WDR1, BAMBI, and GNPDA2) were identified as prognostic-related genes for osteosarcoma, and a novel macrophage-associated risk model was constructed based on these 5 MAGs." (PMID 34188683, 2021). "In general, 5 MAGs (MAP3K5, PML, WDR1, BAMBI, and GNPDA2) correlated with the prognosis of osteosarcoma were screened for the construction of the risk model." (PMID 34188683, 2021). "Gene WDR1 (p = 0.003), PML (p = 0.002), MAP3K5 (p < 0.001), and GNPDA2 (p = 0.030) showed a better prognosis of osteosarcoma in the high expression group." (PMID 34188683, 2021). "The expression of gene WDR1 (p = 0.006), PML (p = 0.005), MAP3K5 (p = 0.010), and GNPDA2 (p = 0.009) were significantly higher in normal bone sample while in osteosarcoma samples, the expression of BAMBI (p = 0.006) was significantly higher." (PMID 34188683, 2021).
pancreatic ductal adenocarcinoma (1 paper, 2025). An infiltrating adenocarcinoma that arises from the epithelial cells of the pancreas. "As for pancreatic ductal adenocarcinoma (PDAC), the upregulation of tRF-GluCTC-0005 enhances the mRNA stability of WD repeat domain 1 (WDR1), thereby promoting cancer cell proliferation, migration, and invasion." (PMID 40565284, 2025).
cancer (14 papers, 2016 to 2025). A tumor composed of atypical neoplastic, often pleomorphic cells that invade other tissues. "The analysis revealed that WDR1 is involved in several cancer-associated pathways, including the AMPK signaling pathway, TGF-β signaling pathway, and Hippo signaling pathway." (PMID 38291031, 2024). "As a protein that assists cofilin-mediated actin filament disassembly, WDR1 is overexpressed in several kinds of cancer." (PMID 38291031, 2024). "Again, the RNA editing level of two sites, chr1:110256304 on GSTM5 and chr4:10080600 on WDR1, on ubiquitination site was significantly different among different subtypes in two cancer types." (PMID 36064557, 2022). "Thus, the present study aimed to evaluate the serum anti-WDR1 antibody (s-WDR1-Ab) titers in patients with various types of cancer compared with healthy donors." (PMID 36875818, 2023). "There are 10 highly significant, direct and physical associators with a confidence score of ≥5.0 namely – RELA, HMOX2, EZH2, p-10Y-ERBB3-1, WDR1, ERRFI1, PRG2, FMR1, DEFA6-(?-100), cytf_human and the majority of the network associators of POTEE are epigenetically activated in many cancers." (PMID 34788504, 2021). "Moreover, VWCE inhibits the growth and migration of cancer cells by limiting the expression of WD-repeat domain 1 (WDR1)." (PMID 33194737, 2020). "TF WDR1 could positively regulate target gene TGFB1 to promote cancer cell proliferation, epithelial–mesenchymal transition (EMT), and migration, and to suppress cancer cell differentiation." (PMID 31126066, 2019). "Notably, we uncovered a previously unprecedented mechanism of WDR1 in cancers." (PMID 32601462, 2020). "As WDR1 enhances CFL1-mediated actin disassembly, the high expression of both WDR1 and CFL1 may synergistically disrupt cancer progression." (PMID 36875818, 2023). "In the analysis of the KEGG pathway, the top five pathways included signal transduction, infectious diseases, cancers, translation, as well as folding, sorting, and degradation, in which WDR1 was the prior participant without exception." (PMID 33194737, 2020).
tumor (10 papers, 2018 to 2024). "Subsequent loss-of-function studies showed that WDR1 contributes to PDAC tumour growth and metastasis." (PMID 32601462, 2020). "WDR1-mediated actin dynamics are required for membrane-associated adhesive junction remodeling in tumor cells." (PMID 33194737, 2020). "Consistent with previous reports, we showed that WDR1 is crucial for tumour growth and invasive potential in vitro and in vivo by shRNA-mediated loss-of-function studies." (PMID 32601462, 2020). "Apart from WDR1, several other oncoproteins and tumour suppressors, such as LDHA, CLIC1, ARPC5, ZYX, RCN1, FHIT and CFTR, were identified in this study." (PMID 32601462, 2020). "As a result, the cytoplasmic immunoreactivity of WDR1 can be merely detected in non-tumour tissues, but gradually upregulated in PDAC as TNM stage increased." (PMID 32601462, 2020). "By using subcutaneous xenograft model, we found that WDR1 knockdown suppressed tumour growth as revealed by changes in tumour volume and weight." (PMID 32601462, 2020). "IHC analysis showed that tumour cells with positive staining of Ki67 in the sh-WDR1 group were markedly attenuated compared with those in the sh-Ctrl group." (PMID 32601462, 2020). "One editing site, chr4:10080600 on WDR1, was under-editing in tumor samples." (PMID 36064557, 2022). "WDR1 knockdown suppressed PDAC tumour growth and metastasis in vitro and in vivo." (PMID 32601462, 2020). "In addition, the oncogenic roles of WDR1 in tumour cell proliferation and invasion are also characterised." (PMID 32601462, 2020). "Furthermore, the in vivo experiment also showed that GA-amide could not inhibit the tumor growth of mice injected with WDR1 deficient U87MG-SLC cells." (PMID 37935665, 2023). "As regards the stage, as the tumor stage progressed, the ratio of s-WDR1-Ab-positive cases vs. negative cases increased." (PMID 36875818, 2023). "Moreover, by luciferase assay, MAPK1 and WDR1 were confirmed to be novel direct targets of miR-1250-5p, and hence the tumor suppressive role of miR-1250-5p was mediated by direct targeting of MAPK1 and WDR1." (PMID 34044822, 2021). "Moreover, PCBP1-AS1 also showed a significant negative correlation with FAM3C, BCL10, SLC16A3, WDR1, and other key molecules of tumor malignant behavior." (PMID 38433921, 2024).
blood disorders (2 papers, 2018 to 2023). "Notably, point mutations in the human AIP1 gene, WDR1, cause severe blood disorders, including reduction and impaired motility of neutrophils." (PMID 37869480, 2023).
infectious disease (2 papers, 2019 to 2020). A disorder directly resulting from the presence and activity of a microbial, viral, or parasitic agent in humans. "DSG1 is directly linked with the cleavage of apoptotic proteins and via ROCK1 with MAPK signaling and infectious diseases (WDR1)." (PMID 31138830, 2019).
cardiovascular disease (1 paper, 2020). "WDR1 is related to the platelet-mediated pathogenesis of cardiovascular disease." (PMID 31991759, 2020).
WDR1 also shares sentences with these, for which no sentence is quoted: actinopathies (2 papers); gastric cancer (2); glioblastoma (2); thyroid cancer (2); autoinflammatory syndrome (1); Behçet disease (1); candidiasis (1); cervical cancer (1); dental caries (1); esophageal squamous cell carcinoma (1); gallbladder cancer (1); head and neck squamous cell carcinoma (1); hyperuricemia (1); infection (1); leukoplakia (1); lupus nephritis (1); lymph node metastasis (1); macrophage activation syndrome (1); male infertility (1); osteoarthritis (1); papillary thyroid carcinoma (1); prostate carcinoma (1); schizophrenia (1).